IL4 (interleukin 4)
Diseases named in the same sentence as IL4 in open-access papers (continued):
Sharing a sentence is not in itself a finding about the gene and the disease.
infection (continued). "First of all, compared to the wildtype MYXV infection-triggered response, ΔM062R infection seems to specifically downregulate the immunosuppressive pathways including IL10 and IL4/IL13 pathways, as revealed by both REACTOME and GO analysis." (PMID 36103568, 2022). "We show that infection with the intestinal nematode H. polygyrus promote homing to and long-term residence of H. polygyrus-specific TH2 cells producing IL-4 and IL-13 in the skin." (PMID 34931000, 2022). "In contrast, Th2 cells producing IL-4, IL-5 and IL-13 are associated with activation of granulocytes involved in allergic reactions as well as activation of B cells and humoral immunity that are usually not effective in intracellular infections such as Mtb nor in anti-tumor responses." (PMID 36591229, 2022). "IL-4, which functions to induce the characteristic Th2 immune response, was significantly increased in both WTSJ group and KOSJ group after infection in mRNA and cytokine level." (PMID 35505421, 2022). "At 14 dpi, ducks were bled to determine the peripheral T-lymphocyte proliferative response to TMUV infection, and the levels of IFN-γ (Th1-type cytokine) and IL-4 (Th2-type cytokine) in serum were also determined." (PMID 35550523, 2022). "Other inflammatory cytokines, such as IL-4, IFN-γ and TNF-α, were also increased in comparison to control animals during the acute phase of infection." (PMID 35337002, 2022). "Next, we evaluated the presence of soluble polypeptides for IFNγ, IL-1β, IL-4, IL-6, IL-8, IL-10, CXCL10, and TNFα in serum of animals following infections with Att-S74-T3Bo and Vir-S74-T3Bo." (PMID 36466866, 2022). "We found cytokines like IFNγ, IL-4, IL-13, IFNβ1, TNFα, and transcriptional regulators such as HIF1α, STAT1, CTCF, TP73, IRF1, MXD1, ATF4, SPI1 mediate macrophage activation upon infection." (PMID 35789215, 2022). "Overall, the authors suggest that in macaques and AGMs animals that survive, henipavirus infection promotes Th1 differentiation, possibly by maintaining low levels of pro-Th2/anti-Th1 IL-4 and higher levels of pro-Th1/anti-Th2 IFN-γ early in infection." (PMID 35632678, 2022). "According to a previous study published in 1997, the authors found that IFN-γ, IL-2, IL-3, IL-4, and IL-5 were significantly changed in BALB/c mice after infection with a small amount of H. nana (100 eggs/mouse) at 14 days." (PMID 35878385, 2022). "A more persistent effect on cardiac fibrosis and systolic function at 35 days post-infection required the combined expression of IL9 with IL3, IL4, IL13, and IL15." (PMID 35508525, 2022). "Compared with patients diagnosed with IVA or IVB infection, HMPV-positive patients had significantly higher levels of IL-4 (p < 0.001 and < 0.001), IFN-γ (p < 0.001 and < 0.001), and TNF-α (p < 0.001 and 0.016)." (PMID 36496397, 2022). "The early stage of animal infection is characterized by Th1/Th2 mixed immune response, which is accompanied with an increase in interferon-γ (IFN-γ), interleukin-4 (IL-4), and related chemokines." (PMID 36003932, 2022). "An exception was the small intestine, where IL-4, IL-10, and IL-17 mRNA exceeded the amount of IFN-γ mRNA in weeks 4 and 6 post-infection." (PMID 36558820, 2022). "We previously utilized deep CAGE (Cap Analysis of Gene Expression) transcriptomics to define the transcriptome of M1 (IFN-γ) or M2 (IL-4, IL-13, IL-4/IL-13) activated BMDMs and during Mtb HN878 infection." (PMID 35895506, 2022). "We also identified a 73% reduction of MIR99AHG expression at 24 h post IL-4/IL-13 stimulation and a 69% reduction at 4 h post Mtb HN878 infection." (PMID 35895506, 2022). "SARS-CoV-2 infection also resulted in many cytokines and chemokines above baseline levels (all P < 0.05) throughout the infection, including IFN-γ, IL-1β, IL-4, IL-28, CXCL10, GM-CSF, LIF, CCL2, CCL7, MIP-1α, MIP-1β, RANTES, IFN-α, and IFN-β." (PMID 35634338, 2022).
infection (continued). "The results showed that the levels of IL-4, IFN-γ and TNF-α increased, and the levels of IL-10 decreased after infection with T. gondii." (PMID 36245502, 2022). "Unlike conventional T cells, the most important characteristic of NKT cells in infection is the rapid activation and substantial production of cytokines such as IFN-γ, IL-10, and IL-4." (PMID 35250975, 2022). "Echinococcus granulosus s.s. has been shown to regulate host immunity by biasing a Th1/Th2 response towards a chronic Th2 response, as the infection was found to induce a marked increase in the transcriptional levels of IFN-γ, IL-2, IL-4, IL-5, and IL-10." (PMID 36289514, 2022). "At the moment of infection, the promastigotes encountered an environment of high TGF-β gene expression and intermediary basal TNF, IL-6, and IL-4 gene expressions." (PMID 34276650, 2021). "For instance, serum and plasma from patients with a mild to moderate infection contained significantly greater levels of MCP-3, IL-1α, TNFβ, IL-4, IL-5, IL-6, IL-8, IL-9, and IL-13 compared to serum and plasma from patients that were critically ill." (PMID 34790978, 2021). "The mRNA expression levels of cytokines IL-2, IL-4, IL-6, IL-8, IL-10, IL-12p40, and IFN-γwere relatively different after P1 infection." (PMID 34988138, 2021). "The concentrations of IL-4, IL-5, TNF, and IFNγ in the BALF of BALB/c pups were also higher, though not statistically different, than in C57BL/6 pups at day 27 post-infection (Figure A2E–G)." (PMID 34682248, 2021). "Several chemokines were induced quickly in the early phase (day 2 p.i.)and maintained at a rather high level through the first week of infection, including CCL2, CCL3, CCL4, CCL7, CXCL10, IL-6, IFN-γ, CCL11, CCL5, TNF-α, CXCL1, IL-4, IL-12p70." (PMID 34379705, 2021). "The percentage of CD4+GATA3+IL-4+ Th2 cells and CD4+CXCR5+ Tfh cells, and IL-4 production in the 8-week-old mice significantly increased on day 5 and day 10 after P. yoelii 17XNL infection." (PMID 33430765, 2021). "Overall, an observable trend of higher serum levels of IL-4 and TNF-α after two cycles of infection-treatment was apparent and diminished during the third cycle." (PMID 34956183, 2021). "T-helper cell (Th1)-type cytokines, such as TNF-α, IL-6 and IL-1β, and Th2-type cytokines, such as IL-10 and IL-4, were differentially expressed in M. fortis and BALB/c mice in the early stage of infection." (PMID 34689797, 2021). "While in rodent models, an increase of IL-4, IL-10 and IFN-γ production was observed by spleen mononuclear cells during early infection, suggesting a mixed Th1/Th2 response." (PMID 34215335, 2021). "To our surprise, we observed similar gene ratios between infection with WT S. Typhimurium and the two T3SS mutants in several cytokine signaling pathways, including interleukin-4 (IL-4), IL-17, and IL-10 signaling pathways (top)." (PMID 34006652, 2021). "At the infection, the promastigotes encountered a favorable skin environment to replicate, with high arginase and TGF-β, as well as an intermediary IL-4 expression and low iNOS." (PMID 34276650, 2021). "In BALB/c MSCs, cell proliferation was reduced after infection by IL-4 (MSCs-IL4) and the control (MSCs-V) vectors, compared to MSCs; however, cell proliferation was significantly enhanced in MSCs-PDGF and MSCs-IL-4-PDGF groups compared to MSC-IL4 group." (PMID 33413614, 2021). "Although this was the case, the noticeable decreases in IL-1β, IL-2, IL-4, IL-12, IL-13, RANTES, TNF-α, and GRO-α observed in patients with lethal SARS-CoV-2 infection suggest that lethal infection results in an exhausted immune response." (PMID 33472985, 2021). "More importantly, IL-4 and stimulated Th2 cells represent a potent B cell growth factor that promotes humoral immunity, which, together with the regulation of Ig genes, would imply that a titer of specific anti-Ceratothoa Igs could be produced systemically during the course of the infection." (PMID 33777043, 2021).
infection (continued). "We conclude from these data that B lymphocytes, activated by two surrogates for CD4+ T helper cells, i.e., IL-4 and CD40L, are more efficient than myeloid DC in mediating HIV-1 trans infection of activated CD4+ T lymphocytes." (PMID 33688006, 2021). "Our results showed an increase in cytokines IL-4 and IL-13 in the BAL of XID mice on the 7th and 19th day of infection." (PMID 34526536, 2021). "As after FCV Challenge I, the median mRNA transcription levels of IL-12p40 (day 2), IL-4 (day 1), and MX1 (mainly day 1 and day 2) were transiently increased, whereas perforin was decreased in the early phase of the infection in both groups." (PMID 34578316, 2021). "Although some studies indicated that IL-4, IL-10, IL-13, and IFN-γ produced by activated T cells in response to infection likely disrupts OC signaling, the RANK-RANKL signaling pathway is central in the differentiation of OCs." (PMID 33735306, 2021). "In contrast, IL-4, IL-5, IL-6, and epidermal growth factor (EGF) reached peak levels late during infection, between 15 and 25 DPI, before dropping considerably at the terminal time point." (PMID 33436428, 2021). "Production of anti-inflammatory cytokines like IL-4, IL-10, IL-13, and TGF-β contributes to the failure of controlling the infection as discussed by Alexander and Bryson." (PMID 34094593, 2021). "Even years after infection, WNV patients that had mild or asymptomatic phenotypes at the time of infection will continue to have higher levels of IL-4 as compared to those with more severe symptoms, suggesting that IL-4 is possibly protective." (PMID 33671257, 2021). "At 6, 24, 48, and 72 h post infection, blood samples were collected, and the serum levels of 10 cytokines (GM-CSF, IL-1β, IL-6, IL-10, TGF-β1, IFNγ, IL-4, IL-8, IL-12p40, and TNF-α) were assessed." (PMID 33665221, 2021). "The proportion and the absolute number of activated CD4+ CD44hiCD62Llo cells that also expressed IL-4 peaked in the BALF, lung digest, and draining lymph nodes (TBLN) of adults at day 11 post-infection and in neonates at day 28 or later post-infection." (PMID 34682248, 2021). "We show that, at the location of infection (popliteal DLN), control mice challenged with L. amazonensis secrete comparable amounts of parasite-specific IFN-γ, IL-4, and IL-10." (PMID 33673117, 2021). "Patients who succumbed to infection produced decreased IL-2, IL-4, IL-12, RANTES, tumor necrosis factor alpha (TNF-α), GRO-α, and MIP-1α relative to patients who survived infection." (PMID 33472985, 2021). "E challenge infection; the number of IFN-γ, IL-2, IL-4, and in particular IL-17 producing splenocytes from mice that had been vaccinated i.n. with c-di-AMP-adjuvanted 5cVAC increased drastically due to re-stimulation with 5cVAC." (PMID 34204170, 2021). "In a proof-of-concept experiment, we showed that IL-4 treatment enhanced SIRPA expression in vitro, thereby restricting virus entry and infection." (PMID 34097709, 2021). "Antibody blocking one day post infection reduced parasite burden one month post-infection, and induced IFN-γ and IL-4 producing cells." (PMID 33776999, 2021). "Reactome analysis of differentially regulated genes from whole tissue RNA-Seq revealed a significant enrichment of genes involved in IL-4 and IL-13 signaling in the infected lung (FDR adjusted P value = 0.03) on day 5 after infection." (PMID 34185704, 2021). "However, because we observed an association of IL-13 but not IL-4 with severe disease in patients, we hypothesized that IL-13 signaling in the lung following infection was contributing to worse outcomes." (PMID 34185704, 2021). "IL-10, IL-4, NO and H2O2 production showed significant enhancement after infection but was observed to be significantly decreased in DHCSA-d and SSG- treated L. donovani at 24 h, 48 h and 72 h." (PMID 32085719, 2020).
infection (continued). "In fibroblasts the infection produces IFN-β, tumor necrosis factor-α (TNF-α), interleukin-4 (IL-4), IL-1-β, chemokine (C-C motif) ligand 2 (CCL2), and chemokine (C-C motif) ligand (CCL5)." (PMID 31979145, 2020). "It has been reported that interleukin (IL)-4, IFN-γ, TNF, IL-13, and IL-1 are involved in anti-infection effects." (PMID 33013763, 2020). "The results indicated that γδ T cells secrete more Th2 cytokines (IL-4, IL-10) and fewer Th1 cytokines (IFN-γ) in response to infection." (PMID 32582168, 2020). "Further, our study findings indicate that CPLE treatment modulates the infection induced cytokine levels of TNFα, IFNγ, IL6 and IL4." (PMID 32074143, 2020). "The Th2 cytokine IL-4 was significantly lower in uninfected and infected ECD mice compared to infected control mice 1- and 2-weeks post infection (p < 0.05)." (PMID 32958779, 2020). "At 6–8 weeks post-infection, IFN-γ production is increased, and the IFN-γ/IL-4 ratio shifts toward Th1 cells in WSX-1−/− and wild type mice, which were accompanied by parasite killing and lesion resolution." (PMID 32849534, 2020). "In cattle also, infection of peripheral blood mononuclear cells (PBMCs) either with N. caninum Nc-Spain7 or Nc-Spain8 induced IFN-γ and IL-4 productions started from 6 dpi." (PMID 32429367, 2020). "This fact was shown using anti-IL-4 antibodies in BALB/C mice, which were infected with L. major at the beginning of the infection." (PMID 32908533, 2020). "The cell-free supernatants after post-infection were analysed for the expression of pro-inflammatory cytokines IL-1β, IL-6 and TNF-α and anti-inflammatory cytokines IL-10, IL-12p40, IL-12p70 and IL-4." (PMID 32295519, 2020). "Mice with NK depletion displayed significantly lower frequencies of IFN-γ+ CD4+ or CD8+ T cells but a higher percentage of IL-4+ CD4+ T cells compared to control mice in both spleen and lung tissues at day 3 after secondary infection." (PMID 32626664, 2020). "The anti-inflammatory cytokines (IL-4, TGFβ) and the enzymes iNOS and IDO also showed significantly higher expression from day one post-infection." (PMID 33322180, 2020). "Among the three epitope-based vaccine groups, the IL-4 levels of Amastin-Gp63 group were the lowest, and the TNF-α levels of that were the highest at 4th and 8th week post-infection." (PMID 32176727, 2020). "To further ascertain the molecular response during the infection of C. sinensis, we measured the CD4+T cell subsets-related cytokines, including IL-10, IL-17, IL-4, IL-2, and TNF-α by ELISA methods." (PMID 33489026, 2020). "The lung homogenates of WT and AhR−/− mice were collected after 96 h, 2 and 10 weeks of infection and used to evaluate the presence of cytokines (IL-12, TNF-α, IL-1β, IL-6, IL-23, IL-2, IFN-γ, IL-4, IL-17, IL-22, TGF-β, IL-10, IL-27, and IL-35)." (PMID 32647342, 2020). "The anti-inflammatory cytokines (interleukin-4 [IL-4], IL-6, and IL-10) and MCP-1/CCL2 were detected early after P. yoeliiyoelii 17XNL infection." (PMID 32958528, 2020). "Indeed, IL-4 produced in response to MTB infection may down-regulate the immune response to limit tissue injury; however, excessive production of this cytokine may result in failure to control infection, thus highlighting the controversy surrounding the role of IL-4 during TB progression." (PMID 33604556, 2020). "Interestingly, direct infection of M(IL-4) macrophages with Mtb results in the establishment of aerobic glycolytic pathway and FM formation, which could be prevented by FAO activation or inhibition of the hypoxia-inducible factor 1-alpha (HIF-1α)-induced glycolytic pathway." (PMID 33002063, 2020). "Upon infection, TNF-α, IL-4, and IL-6 expressions heightened, while IL-3 and IL-1β only appeared in trace amounts." (PMID 32943637, 2020). "Several human VL studies have demonstrated elevated serum levels of IL-4, IL-6, IL-10, IL-12, IL-13, IFN-g, and TNF-a in active disease compared to asymptomatic infection." (PMID 32321156, 2020).
infection (continued). "The ARG1 enzyme, which catalyzes the hydrolysis of arginine to ornithine and urea, is produced in the liver under the stimulation of IL-4, IL-10, and TGF-β, as well as by immune response cells, such as activated neutrophils at infection sites." (PMID 31320834, 2019). "More interestingly, the infection of DCs with Chlamydia would induce the production of the cytokines TNF-α, IL-4, and IL-10 facilitating Th2 immunity and suppressing Th1 development." (PMID 31333596, 2019). "When effector lymphocytes traffic to the inflammatory site, they secrete a large amount of pro-inflammatory cytokines such as IL-4, IL-13, IFN-γ, which induce an intense inflammatory response to clear the pathogen infection." (PMID 31921198, 2019). "Therefore, we can only speculate that the amelioration of plaque-type psoriasis upon IL-4 treatment and the decrease in infections in type 2 diseases upon IL-4R signaling blockade is, at least in part, the direct result of increased or decreased IL-4R signaling on neutrophils, respectively." (PMID 31708926, 2019). "Using a primary human macrophage model of DENV infection, we investigated the effects of maturation with IL-4, DENV-infection and treatment with N-butyl-1-deoxynojirimycin (NB-DNJ) or N-(9-methoxynonyl)-1-DNJ (MON-DNJ) on expression of 11 macrophage receptors." (PMID 31306674, 2019). "Concordant with the murine macrophage data, M(IL-4/IL-13) polarized human MDMs also exhibited a significantly reduced intracellular growth of Mtb HN878 upon miR-143 and miR-365 knockdown at 24 h post-infection." (PMID 30941122, 2019). "These responses were increased in the vaccinated group, and since IL-4 is essential for the development of protective TH1 (IFN-γ) responses to C. albicans, the data we have presented would suggest that volunteers vaccinated with Ty21a may be less susceptible to infection by C. albicans." (PMID 30820452, 2019). "It is noteworthy that at early infection there was an enhanced induction of pro-inflammatory cytokine response of TNF-α and IFN-γ, which gradually reduced to basal levels with the surge of regulatory cytokines, IL-4, IL-10, and TGF-β in later infection." (PMID 31031744, 2019). "The expression analysis also picked up late induction of T-cell-produced IL-4 and IFN-γ by day 7 post-infection." (PMID 31614819, 2019). "Administration of IL-4/IL-13 to macrophages significantly enhanced EBOV GP-dependent viral particle binding and internalization with increases in overall infection." (PMID 31825972, 2019). "As our findings suggested that IL-4/IL-13 treatment enhanced rVSV/EBOV GP infection in an EBOV GP-dependent manner, we evaluated the earliest steps in infection: binding and entry." (PMID 31825972, 2019). "The infection of mast cells with Chlamydia elicits the secretion of cytokines such as TNF-α and IL-4, which promotes the infiltration of immune cells into the airways by opening tight junctions, thereby improving chlamydial propagation." (PMID 31333596, 2019). "Another study demonstrates that patients with severe HAdV-55 infections showed significantly higher levels of blood IL-17+ CD4+ T lymphocytes and higher levels of serum IFN-γ, IFN-α2, IL-4, and IL-10." (PMID 30787914, 2019). "IL-4gfp mice are a valuable tool for tracking Th2 cells because they report IL-4 mRNA independently of IL-4 protein, and retain GFP expression for at least 4-weeks after clearance of infection." (PMID 31815932, 2019). "Among the cytokines analyzed for this study, IL-4, IL-5, IL-10, IL-13, and TGF-b participate in the resolution of infection-related pulmonary inflammation." (PMID 31271354, 2019).